CIP2A (cellular inhibitor of PP2A)
Diseases named in the same sentence as CIP2A in open-access papers (continued):
Sharing a sentence is not in itself a finding about the gene and the disease.
endometrial carcinoma (3 papers, 2018 to 2021). A malignant tumor arising from the epithelium that lines the cavity of the uterine body. "In cervical and endometrial cancer cells, CIP2A expression is mainly regulated by two transcription factors, Elk1 and Ets1, which are both necessary for regulating CIP2A protein levels." (PMID 31214504, 2019). "In addition, we show that human endometrial carcinomas with PPP2R1A, SET and CIP2A mutations or changes in mRNA levels are associated with higher mutation burden and MSI status." (PMID 34911954, 2021).
esophageal squamous cell carcinoma (3 papers, 2011 to 2016). Esophageal squamous cell carcinoma (ESCC) is a type of esophageal carcinoma (EC) that can affect any part of the esophagus, but is usually located in the upper or middle third. "CIP2A is overexpressed in esophageal squamous cell carcinoma and increased CIP2A expression is a predictor of poor survival in esophageal cancer." (PMID 25015035, 2014). "In addition, CIP2A is overexpressed in esophageal squamous cell carcinoma relative to normal tissues, and CIP2A knockdown was found to inhibit tumor cell growth." (PMID 27144172, 2016). "Moreover, in esophageal squamous cell carcinoma, CIP2A was overexpressed in 90% of the specimens studied." (PMID 21610708, 2011).
lung adenocarcinoma (3 papers, 2014 to 2025). A carcinoma that arises from the lung and is characterized by the presence of malignant glandular epithelial cells. "Overexpression of miR-383-5p in H1299 lung adenocarcinoma cells led to G1 cell cycle arrest and apoptosis via CIP2A inhibition, while miR-375 mediated CIP2A repression and subsequent reduced production of oncoprotein MYC in oral tumors." (PMID 37763671, 2023). "MicroRNA-383-5p directly targets CIP2A to suppress lung adenocarcinoma proliferation." (PMID 40943297, 2025). "Above studies collectively indicate the involvement of CIP2A during malignant progression of lung tumors and argue in favor of the fact that IL-10 may aid in promoting tumor aggressiveness via upregulation of CIP2A transcription in lung adenocarcinoma." (PMID 25015035, 2014).
metastatic disease (3 papers, 2015). "Levels of PP2A phosphorylation together with SET and CIP2A protein expression were studied in 24 PCa patients and both were associated with high Gleason scores and presence of metastatic disease." (PMID 26023836, 2015). "Both CIP2A and p-PP2A levels were significantly elevated in the high-risk subgroup, and in those cases with metastatic disease." (PMID 26023836, 2015). "Furthermore, there was no impact of CIP2A expression on OS in patients with metastatic disease." (PMID 25663244, 2015).
nasopharyngeal carcinoma (3 papers, 2014 to 2023). A carcinoma arising from the nasopharyngeal epithelium. "In this study, we investigated the clinical significance of CIP2A and its function in nasopharyngeal carcinoma (NPC)." (PMID 24884612, 2014). "Importantly, the knockdown of CIP2A using siRNAs could inhibit the tumor growth of nasopharyngeal carcinoma in xenografts." (PMID 32321509, 2020).
neuroblastoma (3 papers, 2014 to 2023). Neuroblastoma (NB) is the most common solid, extracranial childhood tumor. "The clinical relevance of CIP2A as a CHK1 effecter protein was validated in several human cancer types including neuroblastoma where CIP2A was identified as an N-MYC-independent prognostic factor." (PMID 25015035, 2014). "Other investigators propose that since MYCN and CIP2A are expressed during embryologic formation of the central nervous system, these two oncogenic proteins could be working together in neuroblastoma tumorigenesis." (PMID 35454859, 2022). "Similarly, the increased expression of CIP2A and MYCN has been associated with a worse prognosis in neuroblastoma, making these compounds exciting therapeutics for a patient population in need of novel therapies." (PMID 35454859, 2022). "In addition, the phosphorylation of CHK1 can upregulate the expression of the CIP2A/p90 gene through phosphorylation of serine 345 of CHK1 via DNA damage response kinases (DNA-PK) in human gastric cancer, ovarian cancer, colon cancer, and neuroblastoma." (PMID 36911405, 2023).
renal carcinoma (3 papers, 2011 to 2026). A carcinoma arising from the epithelium of the renal parenchyma or the renal pelvis. "A498 and KRC/Y renal cancer cells were transfected with CIP2A siRNA and scratched using a Pipette tip 24 h after transfection." (PMID 22075943, 2011).
squamous cell carcinoma (3 papers, 2011). A carcinoma arising from squamous epithelial cells. "We also find that CIP2A is elevated in 17/19 (89.5%) patients with squamous cell carcinoma, whereas 17/35 (48.6%) patients with adenocarcinoma have over-expressed CIP2A (p = 0.003)." (PMID 21655278, 2011).
bladder tumors (2 papers, 2012 to 2014). "In their study CIP2A protein was found specifically expressed in bladder tumor tissue at different cancer stages like most of other solid tumors, and not in adjacent non-tumor bladder tissue." (PMID 25015035, 2014). "The percentage of CIP2A protein positive tissue increased with the grade of bladder tumor, 0% in low malignant potential, 19% in low grade, and 65% in high grade." (PMID 23342256, 2012). "In conclusion, our studies suggest that CIP2A protein is specifically expressed in human bladder tumors." (PMID 23342256, 2012). "Furthermore, CIP2A was specifically expressed in transitional cell carcinoma (TCC) of the bladder tumor tissues but not in adjacent nontumor bladder tissue." (PMID 23342256, 2012).
brain cancer (2 papers, 2014 to 2024). A primary or metastatic malignant neoplasm affecting the brain. "Celecoxib induced apoptosis in glioblastoma tumor cells, the primary malignant tumor of the brain, via suppressing CIP2A/PP2A/Akt signaling axis." (PMID 38500210, 2024). "The reports on the role of CIP2A in brain cancer are limited." (PMID 25015035, 2014).
cholangiocarcinoma (2 papers, 2014 to 2023). A carcinoma that arises from the intrahepatic biliary tree (intrahepatic cholangiocarcinoma) or from the junction, or adjacent to the junction, of the right and left hepatic ducts (hilar cholangiocarcinoma). "CIP2A is overexpressed in human cholangiocarcinoma tissues, which correlated with poor prognosis and the expression of CIP2A protein was an independent prognostic factor for cholangiocarcinoma patients." (PMID 25015035, 2014).
cutaneous melanoma (2 papers, 2015 to 2023). A primary melanoma arising from atypical melanocytes in the skin. "We examined CIP2A expression in cutaneous melanomas, its association with clinicopathological parameters and mapped molecular mechanisms regulated by CIP2A in vitro." (PMID 25663244, 2015).
esophageal adenocarcinoma (2 papers, 2014). A malignant tumor with glandular differentiation arising predominantly from Barrett mucosa in the lower third of the esophagus. "The expression of CIP2A and c-MYC were associated with one another, and in most cases of esophageal adenocarcinoma they were found to be co-overexpressed." (PMID 25015035, 2014).
esophageal cancer (2 papers, 2010 to 2014). A primary or metastatic malignant neoplasm involving the esophagus. "Auto-antibodies against CIP2A were detected in 13%, 5% and 3% of the sera of hepatocellular, gastric and esophageal carcinomas, respectively." (PMID 20964854, 2010).
Hypoglycemia (2 papers, 2022 to 2025). A decreased concentration of glucose in the blood. "Mechanistically, metformin activates the PP2A-GSK3β-MCL-1 pathway by inhibiting cancerous Inhibitor Of PP2A (CIP2A), a PP2A inhibitor, and hypoglycemia upregulates the B56δ, a PP2A regulatory subunit, eventually, the active PP2A-B56δ has higher affinity for GSK3β." (PMID 36484892, 2022).
idiopathic pulmonary fibrosis (2 papers, 2022 to 2025). Idiopathic pulmonary fibrosis (IPF) is a nonneoplastic pulmonary disease that is characterized by the formation of scar tissue within the lungs in the absence of any known cause. "Equally, transforming growth factor beta (TGF-β) signaling, a key driver of pulmonary fibrosis, is linked to PP2A and CIP2A signaling." (PMID 41155727, 2025). "Several studies also suggest that CIP2A could play a role in fibrotic pathways and epithelial-to-mesenchymal transition (EMT), which occur in idiopathic pulmonary fibrosis (IPF) or fibrosis secondary to chronic lung injuries." (PMID 41155727, 2025).
medulloblastoma (2 papers, 2018 to 2022). A malignant, invasive embryonal neoplasm arising from the cerebellum. "IHC demonstrated that PP2A and its endogenous inhibitors, PP2A inhibitor 2 (I2PP2A/SET) and cancerous inhibitor of PP2A (CIP2A), were present in all three medulloblastoma PDXs." (PMID 29720672, 2018). "In the current study, we demonstrated that PP2A and its two endogenous inhibitors I2PP2A/SET and CIP2A are expressed in medulloblastoma PDX cells." (PMID 29720672, 2018). "Prior investigations from our lab found that treatment with the PP2A activator, FTY720, led to decreased CIP2A expression in two of the three medulloblastoma PDXs utilized, suggesting the effect of PP2A activation on CIP2A expression may be cell line specific." (PMID 35454859, 2022). "In addition, FTY720 treatment of human medulloblastoma PDXs resulted in activation of PP2A in the face of decreased overall PP2A protein expression, but changes in I2PP2A/SET or CIP2A expression were not consistently seen." (PMID 29720672, 2018).
metastatic melanoma (2 papers, 2015 to 2024). A melanoma that has spread from its primary site to another anatomic site. "Expression of CIP2A protein was analyzed by immunohistochemistry in a panel of paraffin-embedded benign nevi, primary and metastatic melanomas." (PMID 25663244, 2015).
multiple sclerosis (2 papers, 2022 to 2025). A progressive autoimmune disorder affecting the central nervous system resulting in demyelination. "As statedin the introduction, FTY720 is an FDA-approved immunosuppressant for multiple sclerosis, which has been described to downregulate CIP2A." (PMID 35329936, 2022). "Fingolimod (FTY720), an immunomodulatory drug for multiple sclerosis, demonstrates anticancer potential by activating PP2A and potentially inhibiting CIP2A activity." (PMID 41155727, 2025).
myelodysplastic syndrome (2 papers, 2014 to 2017). A clonal hematopoietic disorder characterized by dysplasia and ineffective hematopoiesis in one or more of the hematopoietic cell lines. "There are reports of changes in the expression of CIP2A in both solid tumors and Myelodysplastic Syndromes." (PMID 25015035, 2014).
oral squamous cell carcinoma (2 papers, 2013 to 2024). "P90, alternatively identified as KIAA1524 and Cancerous Inhibitor of PP2A (CIP2A), exhibits elevated expression levels in both oral squamous cell carcinoma (OSCC) cell lines and tissues." (PMID 38920585, 2024). "We tested the presence of CIP2A in human leukoplakia samples, which can undergo malignant conversion into aggressive oral squamous cell carcinoma." (PMID 38920585, 2024).
ovarian tumour (2 papers, 2011 to 2025). "Using an OvCa single cell database, of 84 ovarian tumour patients -primarily high-grade serous carcinoma (HGSC)- from 16 publicly available studies21we demonstrate that CIP2A is expressed in a wide range of cells i.e., T/B/mast/myeloid/ epithelial/endothelial cells, pericytes and fibroblasts." (PMID 40594400, 2025). "Interestingly, the 5-year survival for patients with cytoplasmic CIP2A overexpressed (32%) was similar to the 5-year survival of the type II ovarian tumours (30%)." (PMID 21897396, 2011).
pancreatic ductal adenocarcinoma (2 papers, 2014 to 2016). An infiltrating adenocarcinoma that arises from the epithelial cells of the pancreas. "In this study, we evaluated the expression of CIP2A and its relationship to the prognosis and drug resistance in pancreatic ductal adenocarcinoma." (PMID 26894380, 2016). "Using immunohistochemical staining, we investigated the expression of CIP2A protein in 72 cases of human pancreatic ductal adenocarcinoma (PDAC) tissue and 27 cases of adjacent normal pancreatic tissue." (PMID 26894380, 2016). "COX regression analysis indicated that expression of CIP2A was an independent prognostic factor for pancreatic ductal adenocarcinoma." (PMID 26894380, 2016). "Immuno-histochemical staining demonstrated that CIP2A expression correlated with poor tumor differentiation, TNM stage and lymph node metastasis in pancreatic ductal adenocarcinoma." (PMID 25015035, 2014).
Parkinson disease (2 papers, 2022 to 2025). A progressive degenerative disorder of the central nervous system characterized by loss of dopamine producing neurons in the substantia nigra and the presence of Lewy bodies in the substantia nigra and locus coeruleus. "There is also some evidence suggesting that CIP2A may play a role in neurodegenerative diseases such as Parkinson’s Disease." (PMID 41155727, 2025). "In a study of patients with Parkinson’s disease, lower levels of CIP2A were observed." (PMID 41155727, 2025).
Pleural effusion (2 papers, 2016 to 2021). The presence of an excessive amount of fluid in the pleural cavity. "One dasatinib-treated patient with low CIP2A progressed; this patient had a high Sokal score and an intermediate ELTS score and frequent treatment interruptions due to recurrent pleural effusions." (PMID 33947031, 2021).
rectal cancer (2 papers, 2018). A primary or metastatic malignant neoplasm that affects the rectum. "In conclusion, these results suggest that by contributing to radiosensitivity of cancer cells, low CIP2A protein expression level associates with a favorable response to long‐course (C)RT in rectal cancer patients." (PMID 29441695, 2018). "In conclusion, our results suggest that low CIP2A protein expression level is associated with a favorable response to long‐course (C)RT and with increased disease‐specific survival in rectal cancer." (PMID 29441695, 2018). "CIP2A expression contributes to radiotherapy resistance in rectal cancer." (PMID 30063110, 2018). "Thus, the validity of CIP2A as a predictive biomarker for preoperative treatment response in rectal cancer warrants further investigation in the pursuit of providing more personalized treatment modalities for rectal cancer patients." (PMID 29441695, 2018).
small cell lung carcinoma (2 papers, 2015 to 2025). Small cell lung cancer (SCLC) is a highly aggressive malignant neoplasm, accounting for 10-15% of lung cancer cases, characterized byrapid growth, and early metastasis. "Enhanced CIP2A expression is frequently overexpressed in non-small cell lung cancer (NSCLC) and small cell lung cancer (SCLC), where it promotes tumor progression." (PMID 41155727, 2025).
acute pancreatitis (1 paper, 2025). An acute inflammatory process that leads to necrosis of the pancreatic parenchyma. "Inhibiting CIP2A expression with TD52 and ethoxysanguinarine decreased the release of inflammatory cytokines, reduced macrophage apoptosis, promoted macrophage autophagy regulation, and inhibited the Akt-mTOR pathway in an in vitro model of acute pancreatitis." (PMID 41155727, 2025). "Inhibiting CIP2A expression with the CIP2A inhibitor TD52 reduced the release of inflammatory cytokines and apoptosis in macrophages and promoted macrophage autophagy regulation possibly via Akt/mTOR inhibition in an acute pancreatitis model." (PMID 41155727, 2025).
acute respiratory distress syndrome (1 paper, 2025). Progressive and life-threatening pulmonary distress in the absence of an underlying pulmonary condition, usually following major trauma or surgery. "CIP2A is also a major regulator of immune responses, especially nuclear factor kappa B (NFκB) and cytokine pathways, which could make it relevant in diseases such as pneumonia, acute lung injury (ALI), and acute respiratory distress syndrome (ARDS)." (PMID 41155727, 2025).
amyloidosis (1 paper, 2022). A disorder characterized by the localized or diffuse accumulation of amyloid protein in various anatomic sites. "In our previous study, we have identified that CIP2A is upregulated in AD brains and promotes AD-like tauopathy and amyloidosis through inhibiting PP2A’s dephosphorylating effects on tau/APP." (PMID 35286657, 2022).
asthma (1 paper, 2025). "Despite PP2A being linked to asthma and allergy, CIP2A has not been directly studied in this context." (PMID 41155727, 2025). "In conditions such as asthma and allergic airway diseases, CIP2A may modulate immune responses by either directly influencing immune cells like T cells and macrophages or by altering upstream cytokine signaling pathways, which subsequently modulate their activity." (PMID 41155727, 2025).
astrocytoma (1 paper, 2014). "CIP2A depletion in the astrocytoma cell lines inhibited cell growth, reduced anchorage-independent cell growth and increased apoptosis." (PMID 25015035, 2014). "Although this study indicates role of CIP2A as a clinically relevant oncoprotein and point out that CIP2A may be a promising therapeutic target of astrocytoma, further studies in this direction are required to draw a conclusion." (PMID 25015035, 2014).
benign ovarian tumours (1 paper, 2025). "CIP2A is overexpressed in OvCa patients, with metastatic patients having significantly higher expression when compared to patients with malignant and benign ovarian tumours." (PMID 40594400, 2025). "Our results show that although age and stage (grouped as early vs. late) do not affect expression; metastatic OvCa patients have significantly higher expression of CIP2A when compared to malignant OvCa samples (p = 0.0366) and benign ovarian tumours (p = 0.0326)." (PMID 40594400, 2025).
benign prostatic hyperplasia (1 paper, 2010). A non-cancerous nodular enlargement of the prostate gland. "Interestingly, auto-antibodies against CIP2A were detected in over 30% of sera from prostate adenocarcinoma patients while only 1.5% of benign prostatic hyperplasia (BPH) patients were found to be positive for these antibodies." (PMID 20964854, 2010).
bronchiolitis obliterans (1 paper, 2025). "In an animal model of bronchiolitis obliterans, inhibition of CIP2A signaling was observed to reduced NFκB signaling, inflammatory cell infiltration into the lungs, and secretions of IL-1β, IL6, and TNFα." (PMID 41155727, 2025). "Treatment with ethoxysanguinarine (a CIP2A inhibitor) reduced CIP2A expression in a 2,3-butanedione-induced rat model of bronchiolitis obliterans, which coincided with reduced EMT." (PMID 41155727, 2025). "Finally, a recent article observed that CIP2A expression was enhanced in a 2,3-butanedione-induced rat model of bronchiolitis obliterans, and treatment with ethoxysanguinarine reduced the CIP2A expression, intraluminal occlusion, inflammatory infiltration, and fibrosis." (PMID 41155727, 2025). "Altered CIP2A signaling is also reported in chronic obstructive pulmonary disease (COPD) and recently in a model of bronchiolitis obliterans." (PMID 41155727, 2025).
chronic obstructive pulmonary disease (1 paper, 2025). A chronic and progressive lung disorder characterized by the loss of elasticity of the bronchial tree and the air sacs, destruction of the air sacs wall, thickening of the bronchial wall, and mucous accumulation in the bronchial tree. "Interestingly, CIP2A expression or signaling is also observed in several non-cancerous pulmonary diseases, such as chronic obstructive pulmonary disease." (PMID 41155727, 2025).